BECN1 (beclin 1)
Diseases named in the same sentence as BECN1 in open-access papers (continued):
Sharing a sentence is not in itself a finding about the gene and the disease.
prostate tumors (11 papers, 2014 to 2024). "Tumor suppressor role of Beclin-1 is validated genetically in breast, ovarian and prostate tumors, as mono-allele deletion of Beclin-1 occurs." (PMID 36160153, 2022). "For example, the mono-allelic deletion of BECN1 (a gene that encodes Beclin1, a mammalian orthologue of yeast Atg6/vacuolar protein sorting (Vps)-30) has been detected in many types of tumor specimens such as in human breast, ovarian, and prostate tumors." (PMID 30717078, 2019). "Deletions of Beclin 1 have been described in specimens of human breast, ovarian and prostate tumours." (PMID 28423666, 2017). "The tumor suppressor function of Beclin-1 is supported by the genetic evidence that Beclin-1 is monoallelically deleted in breast, ovarian, and prostate tumors." (PMID 28536348, 2017). "High frequency of monoallelic BECN1 gene deletion has been found in up to 75% cases of human ovarian, breast and prostate tumours." (PMID 28060760, 2017). "Monoallelic deletion of BECN1 has been detected in 40–75% cases of human breast, ovarian, and prostate tumors, and thus Beclin-1 is considered as a tumor suppressor gene." (PMID 25317422, 2014). "Moreover, Becn1+/−mice do not develop prostate tumours, unlike the spontaneous generation of liver and lung carcinomas observed in these mice." (PMID 38910881, 2024).
amyloid (10 papers, 2013 to 2023). "Decreased beclin-1 in mice models of AD- and HD-related amyloidosis causes impaired macroautophagy, increased inclusion bodies, and general neuronal deficits, aspects reversed through ectopic beclin-1 expression." (PMID 33490063, 2020). "Beclin-1, an autophagy-related protein, decreases with age in the brains of AD models, and increased levels of Beclin-1 ameliorate amyloid pathology." (PMID 36994671, 2023). "Genetic modification indicates that the down-regulation of Becn-1 increases intraneuronal Aβ production and extracellular Aβ deposition, whereas the enhancement of Beclin-1 expression decreases amyloid pathology in APP transgenic mice." (PMID 35241159, 2022). "For example, the key autophagy‐related protein BECN1 (beclin‐1) had been reported to be reduced in the brains from early AD patients, and overexpression of BECN1 reduced amyloid pathology in APP mice." (PMID 31858697, 2020). "Abrogating Beclin 1 cleavage enables neurons to survive after excitotoxic insult, caspase activation and in the context of amyloidosis." (PMID 30594228, 2018). "Deletion of Beclin 1 in mice has been reported to increase Aβ deposits, to decrease neuronal autophagy and to promote neuronal degeneration, while gene therapy using lentivirus expressing Beclin 1 reduces amyloid pathology in APP transgenic mice." (PMID 23951225, 2013). "Here we show that AD animals have high levels of insoluble parkin and decreased parkin-Beclin-1 interaction, while peripheral administration of TKIs, including Nilotinib and Bosutinib, increases soluble parkin leading to amyloid clearance and cognitive improvement." (PMID 23737459, 2013). "Thus, we consequently crossed these mice with amyloid mouse models, including 5XFAD and PDAPP mice, to study the function of Becn1-mediated autophagy in AD." (PMID 28806762, 2017).
cerebral infarction (10 papers, 2015 to 2025). An ischemic condition of the brain, producing a persistent focal neurological deficit in the area of distribution of the cerebral arteries. "When treated with a PINK1 inhibitor, the expression of LC3B and Beclin-1 is decreased, the mitochondrial translocation of Parkin is lessened, and the volume of cerebral infarction is increased significantly." (PMID 34335233, 2021). "Previous research has proved that autophagy inhibition by Beclin-1 knockdown can attenuate secondary thalamic damage after focal cerebral infarction." (PMID 25729215, 2015). "Furthermore, GM1 mediated cerebral infarction reduction was blocked by Tat–Beclin-1." (PMID 26751695, 2016). "Compared with IR group, NDS, cerebral infarction volume, brain water content, apoptosis rate, and MDA and ROS levels decreased, while SOD, HIF-1α, BNIP3, LC3-II and Beclin-1 levels increased in IL-4 group (P<0.05)." (PMID 36910409, 2022). "2ME2 and IL-4+2ME2 groups had decreased NDS, cerebral infarction volume, brain water content, apoptosis rate and MDA, ROS, HIF-1α, BNIP3, LC3-II and Beclin-1 levels, but increased SOD level compared with those of IL-4 group (P<0.05)." (PMID 36910409, 2022). "Tat-Beclin-1 did not clearly increase the infarct volume nor worsen the neurobehavioral functions compared to MCAO rats; however, the effects of GM1 on cerebral infarction reduction and neurobehavioral improvement were abolished by Tat-Beclin-1(P<0.05)." (PMID 26751695, 2016).
esophageal squamous cell carcinoma (10 papers, 2013 to 2025). Esophageal squamous cell carcinoma (ESCC) is a type of esophageal carcinoma (EC) that can affect any part of the esophagus, but is usually located in the upper or middle third. "For esophageal squamous cell carcinoma, an evident higher 3-year OS rate (near to 63.0%) was observed in Beclin 1 positive subgroup, particularly in the patients with HIF-1α low expression context." (PMID 24303007, 2013). "Additionally, HMGB1 promotes beclin 1 (BECN1)-dependent autophagy, which subsequently promotes radioresistance in oral squamous or esophageal squamous cell carcinoma (ESCC)." (PMID 41164196, 2025).
Huntington disease (10 papers, 2015 to 2024). Huntington disease (HD) is a rare neurodegenerative disorder of the central nervous system characterized by unwanted choreatic movements, behavioral and psychiatric disturbances and dementia. "Mutant huntingtin (Htt) forms, the main source of neurotoxic activities of Huntington disease (HD), are sensitive to beclin 1 level as demonstrated by the increased accumulation of Htt upon beclin 1 deficiency." (PMID 26999089, 2016). "We also show that ATG14-associated Vps34 activity and ULK1-mediated phosphorylation of ATG14 and Beclin 1 are compromised in the Q175 mouse model of Huntington’s disease." (PMID 27938392, 2016). "Despite this peptide has been recommended for inducing autophagy as a therapeutic strategy for pathologies such as Huntington’s disease or cancer, Tat-BECN1 could also promote toxicity (autosis) in a concentration dependent manner that is cell type specific." (PMID 38796484, 2024). "Beclin 1 activity is also affected in Huntington disease (HD)." (PMID 28611593, 2017).
ovarian tumors (10 papers, 2015 to 2024). "We initially hypothesized that the maintenance of Beclin-1 expression underlined its importance for autophagy in ovarian tumor cells." (PMID 26239434, 2015). "Since ovarian tumors appear capable of undergoing autophagy despite prevalent BECN1 heterozygous loss, we wondered if Beclin-1 was actually downregulated in this context and whether it was still required for autophagy induction." (PMID 26239434, 2015). "We found evidence that single-cells within a BECN1+/- ovarian tumor are more variably aneuploid cell-to-cell than a similarly analyzed BECN1+/+ tumor." (PMID 35846434, 2022). "Although loss of BECN1 is purported to be solely a passenger mutation "piggybacking" on a BRCA1 deletion during tumorigenesis, we directly observed formation of earlier ovarian tumors in Becn1+/- MISIIR-TAg+ mice compared to Becn1+/+ MISIIR-TAg+ mice." (PMID 31923184, 2020). "Based on aCGH data that was processed to yield gene-level copy-number calls, 433/569 ovarian tumours (76 %) possessed hemizygous deletion of the BECN1 gene." (PMID 26239434, 2015). "We have demonstrated that ovarian tumors and cell lines maintain Beclin-1 protein expression, and that in vitro cultures of these cells retain the capacity to upregulate autophagy." (PMID 26239434, 2015). "Taken together, these data demonstrate that despite its sustained expression, Beclin-1 is dispensable for autophagy induction in ovarian tumor cells in vitro, yet may be retained to promote cell viability by a mechanism independent of autophagy or apoptosis regulation." (PMID 26239434, 2015). "None of these studies, however, evaluated Beclin-1 protein expression in ovarian tumors with respect to gene copy-number as we have done using TCGA datasets." (PMID 26239434, 2015).
renal carcinoma (10 papers, 2011 to 2025). A carcinoma arising from the epithelium of the renal parenchyma or the renal pelvis. "The downregulation of ATG7 and beclin-1 also prevented the combined treatment-induced apoptosis in human renal carcinoma Caki, ACHN, and A498 cells." (PMID 29849119, 2018). "In our study, we observed that autophagy was obviously activated by paclitaxel via the MAPK pathway and beclin 1 protein in FLCN-deficient renal cancer cells, but not in FLCN-expressing cells." (PMID 24305604, 2013). "Our results showed that the knockdown of IFI35 increased the expression of autophagy-related genes (Beclin-1, LC3-II, and ATG-5) in renal cancer cells." (PMID 35740527, 2022). "Although ABC294640 increased Beclin-1 expression in kidney carcinoma cells, it did not affect Beclin-1 expression in CCA cells." (PMID 26956050, 2016).
brain tumors (9 papers, 2008 to 2025). "Under glutamate deprivation and hypoxic conditions, phosphoglycerate kinase 1 (PGK1) is acetylated at lysine 388 by NAA10/ARD1, which subsequently leads to the interaction of PGK1 with Beclin 1, causing phosphorylation of Beclin 1 at serine 30, thereby inducing autophagy and brain tumour formation." (PMID 39778006, 2025). "In the context of brain tumors, expression of BECN1, a specific autophagy gene, is lower in GBMs compared to lower grade astrocytomas and normal brain tissues." (PMID 29692710, 2018). "For example, BECN1, an autophagy-related gene required for autophagosome formation, seems to act as a tumor suppressor, and certain brain tumors have been attributed to insufficient BECN1 expression." (PMID 28771183, 2017). "In brain tumors, Beclin 1 levels have beenfound to decrease with malignancy." (PMID 19421400, 2008).
cholangiocarcinoma (9 papers, 2013 to 2023). A carcinoma that arises from the intrahepatic biliary tree (intrahepatic cholangiocarcinoma) or from the junction, or adjacent to the junction, of the right and left hepatic ducts (hilar cholangiocarcinoma). "As to the association of Beclin-1 and cholangiocarcinoma, our histopathological retrospective study found that higher expression of Beclin-1 was significantly associated with a poor OS rate and recurrence-free rate." (PMID 30849962, 2019). "We found that Beclin 1 was lowly expressed in 126 (70%) cholangiocarcinoma patients, consist of 72 ICC and 54 ECC." (PMID 24303007, 2013). "Beclin 1 high or low expression had the similar 3-year OS rate (high VS low: 21.4% VS 33.0%, P = 0.25) for the overall cholangiocarcinoma patients, Beclin 1 high expression predicted a favorable 3-year PFS (high VS low: 69.1% VS 46.8%, P = 041)." (PMID 24303007, 2013). "However, recent studies found that Beclin-1 was negatively correlated with disease progression in cholangiocarcinoma patients." (PMID 30849962, 2019). "for Beclin 1 highly expressed cholangiocarcinoma patients, particularly for ECC subgroup that had favorable OS and PFS, postoperative adjuvant chemotherapy might mean overtreatment to these patients." (PMID 24303007, 2013). "Moreover, Beclin 1 high expression was correlated with a favorable PFS for cholangiocarcinoma." (PMID 24303007, 2013). "When stratified the cholangiocarcinoma patients into low Beclin 1 ICC and high Beclin 1 ECC subgroups, multivariate analysis showed that Beclin 1 was an independent prognostic biomarker both in OS (P = 0.043; HR, 0.752) and PFS (P = 0.004; HR, 0.541)." (PMID 24303007, 2013). "Survival analysis showed that, compared with the high expression subset, Beclin 1 low expression was correlated with a poorer 3-year progression-free survival (PFS, 69.1% VS 46.8%, P=041) for cholangiocarcinoma." (PMID 24303007, 2013). "In lymph node negative (N0) cholangiocarcinoma subgroup, Beclin 1 was relatively higher expressed than that of lymph node positive (N1) subset." (PMID 24303007, 2013). "Importantly, Beclin 1 low expression predicted an inferior PFS, and was a negative prognostic biomarker for cholangiocarcinoma." (PMID 24303007, 2013).
chronic myeloid leukemia (9 papers, 2017 to 2025). "An investigation has assessed if a treatment joining the oncolytic action of an adenoviral vector with the concomitant presence of the gene Beclin-1 presented an improvement for chronic myeloid leukaemia (CML) cells resistant to chemotherapy." (PMID 33704184, 2020). "For instance, using BECN1-induced autophagy, the oncolytic viruses significantly increased BCR/ABL protein expression, and significantly improved the pathology of chronic myeloid leukemia, suggesting that BECN1 may offer a new target for clinical implications." (PMID 36078029, 2022). "Several autophagy-related genes (Beclin-1, Agt4, and Atg5) are upregulated, and the silencing of these genes negatively affects cell survival; as a result, the extent of autophagy in chronic myeloid leukemia (CML) appears to be related to the status of CSCs in the tumor." (PMID 32391363, 2020).
fibrosis (9 papers, 2017 to 2025). the formation of excess fibrous connective tissue in an organ or tissue in a reparative or reactive process. "In addition, we detected the protein levels of LC3, P62 and Beclin-1 in the CCl4 fibrosis model and cultured HSC-T6 cells." (PMID 37790613, 2023). "PUMA deficiency did not affect the levels of Fas, FasL, and BECN1, but downregulated cleaved caspase-3 in CCl4-induced mouse fibrosis." (PMID 33980818, 2021). "In addition, treatment of empagliflozin in Beclin 1 haplodeficient mice further ameliorated DNA damage, cardiac fibrosis, and cardiomyocyte injury." (PMID 33138323, 2020). "qRT‐PCR and WB indicated that the expression levels of Beclin‐1 and LC3II/LC3I were decreased, and p62 was increased in the TGF‐β‐induced fibrosis cell model, whereas these trends were reversed by Adenosine." (PMID 41179361, 2025).
injury (9 papers, 2010 to 2025). Damage inflicted on the body as the direct or indirect result of an external force, with or without disruption of structural continuity. "This suggests that BECN1 plays a key role in the protective effect of Gly-Arg against pharmacological Cis-induced liver injury." (PMID 37745084, 2023). "Beclin-1 is a key protein that regulates autophagy and cell death, and studies have revealed that Beclin-1 is differentially expressed in the renal tissues of rat models of renal ischemia-reperfusion injury." (PMID 30305832, 2018). "They found a recruitmention of pCaMKII to the membrane rafts and a translocation of Beclin-1 export membrane microdomains was rapidly induced by moderate traumatic brain injury." (PMID 30319532, 2018). "Overexpression of Beclin 1 has been observed after brain injury; this suggests increased autophagy plays a crucial role, exerting neuroprotective effects by removing injured cells and components." (PMID 29271925, 2017). "The most common mechanisms for upregulating the autophagic flux after traumatic brain injury include the following: increased levels of Beclin 1 protein and a decrease in the Beclin-1/BCL2 complex; enhanced type-III PI3 kinase activity; and autophagic processes." (PMID 34738222, 2022). "In hypoxia-ischemia-induced brain injury, Beclin-1 has been observed to co-localize with neurons but not GFAP-positive cells." (PMID 34684832, 2021).
renal cell carcinoma (9 papers, 2019 to 2025). "A poorer prognosis of patients expressing low Beclin 1 levels has also been reported in multiple tumor entities, such as breast, ovarian, oral, gastric, and renal cell carcinoma." (PMID 31877888, 2019). "For instance, AIM2 was capable of inhibiting the proliferation, invasion and migration of renal cell carcinoma (RCC) cells by upregulating autophagy-related genes (Bcl-2, Beclin-1, LC3-II and ATG5)." (PMID 31492049, 2019). "In renal cell carcinoma, TQ activates AMPK, suppresses mTOR, and increases LC3 and Beclin-1 expression, leading to autophagy, which suppresses cell migration and invasion; importantly, inhibition of autophagy reverses these anti-metastatic effects." (PMID 41303508, 2025). "In renal cell carcinoma, CCL2 secreted by M2 macrophages increases muscleblind like splicing regulator 2 (MBNL2) expression, which in turn stabilizes B-cell lymphoma 2 (Bcl-2) mRNA, leading to the inhibition of Beclin 1-dependent autophagy and endowing RCC cells with invasion properties." (PMID 39286635, 2024). "In several carcinoma models, including renal cell carcinoma 786-O, ACHN, and SASVO3 head-and-neck cells, TQ activates AMPK, leading to downstream mTOR inhibition and increased LC3-II/Beclin-1 expression, consistent with autophagy induction, that culminates in autophagic cell death." (PMID 41303508, 2025).
type 2 diabetes (9 papers, 2015 to 2025). "Notably, autophagy abnormality has been recently associated with metabolic disorders, such as type 2 diabetes, and the BECN1 protein was shown to regulate insulin secretion." (PMID 32804959, 2020). "In HFD-STZ-induced type 2 diabetes, Beclin-1 levels were considerably upregulated in the adipose tissue of diabetic rats than in control tissues, indicating the start of autophagosome formation and inducing the cellular autophagic process." (PMID 38698047, 2024). "This pA-QTL was colocalized both with eQTL signals for BECN1 and GWAS signals for type 2 diabetes." (PMID 32804959, 2020). "Previous reports have revealed increases in LC3II and Beclin-1 expression and the LC3II/LC3I ratio in the myocardium of mice with type 2 diabetes induced by a high-fat diet plus streptozotocin." (PMID 32509142, 2020).
Cirrhosis (8 papers, 2012 to 2021). A chronic disorder of the liver in which liver tissue becomes scarred and is partially replaced by regenerative nodules and fibrotic tissue resulting in loss of liver function. "It was demonstrated that hyperammonemia can increase the autophagy markers such as beclin-1, LC3II and p62 and contributes to muscle loss in sarcopenia with cirrhosis condition." (PMID 28055974, 2017). "Beclin-1 expression also negatively correlated with HCC with cirrhosis background (P = 0.029)." (PMID 24885292, 2014). "In this study, expression level of Beclin-1 was negatively correlated with HCC Edmondson grades, HCC with cirrhosis background and vascular invasion." (PMID 24885292, 2014). "Immunohistochemistry and in situ hybridization were used to detect the expression of hepatic BECN1 and NF-kBp65 in patients with HCC, hepatitis B virus (HBV) or cirrhosis, as compared with the expression levels in healthy subjects." (PMID 23833647, 2013). "The overexpression of BECN1 may prevent hepatocyte apoptosis, in that HBV infection has been demonstrated to be significant in the development and prognosis of hepatitis, cirrhosis and HCC." (PMID 23833647, 2013). "Similarly, a meta-analysis of 1124 HCC patients identified Beclin 1 as a prognostic marker based on the negative correlation between Beclin 1-positive expression and alpha-fetoprotein, cirrhosis, and vascular invasion." (PMID 33712559, 2021). "Similarly, Beclin-1 expression was significantly lower in HCC with vascular invasion and cirrhosis background than HCC without vascular invasion and cirrhosis." (PMID 24885292, 2014). "Similarly, the positive rate of Beclin-1 expression in HCC with cirrhosis was 69.9% (58/83) and without cirrhosis was 85.0% (17/20)." (PMID 24885292, 2014).